STAT3 (signal transducer and activator of transcription 3)
Diseases named in the same sentence as STAT3 in open-access papers (continued):
Sharing a sentence is not in itself a finding about the gene and the disease.
tumor (continued). "IL-17 activates Stat3 in tumor and tumor stromal cells through an IL-6-dependent mechanism, upregulating prosurvival and proangiogenic genes." (PMID 38339010, 2024). "Mechanistically, senescent tumor cells derived IL-6 induces the upregulation of TAMs CD73 expression through JAK/STAT3 signaling pathway." (PMID 38323313, 2024). "In summary, these research findings emphasize the important role of the lncRNA/IL/STAT3 axis in tumor development." (PMID 38172648, 2024). "Consistent with this conclusion, it has been shown that the SIN3A promotes cell survival in different cancers by forming a complex with STAT3 to silence tumor repressor genes." (PMID 38948024, 2024). "This is achieved through the suppression of STAT3 signaling in dendritic cells, which indirectly reduces IL-6 production by tumor cells." (PMID 39660124, 2024). "The cluster counts for intra-vesicular proteins show the statistically significant overexpression (p < 0.05) of STAT3 in the tumor group compared to that in the hyperplasia one." (PMID 39120316, 2024). "CircUBE2Q2, an upregulated regulatory circRNA in GC, promotes tumor metastasis by inhibiting the STAT3 pathway through the circUBE2Q2-miR-370-3p-STAT3 axis and exosomal communication." (PMID 40809111, 2024). "In summary, we have demonstrated that aberrantly activated mTORC1 contributes to ferroptosis resistance and tumor growth by regulating of the ERO1α/IL-6/STAT3/SLC7A11 signaling pathway." (PMID 38610018, 2024). "Previous research has suggested that STAT3 can promote the transcription of VEGF-A to potentiate tumor angiogenesis." (PMID 39198402, 2024). "Curcumin, from turmeric, inhibits NF-κB and STAT3 signaling, attenuating tumor progression and enhancing anticancer immunity by stabilizing PD-L1 and reducing CSN5 activity, a deubiquitinase modulating PD-L1 ubiquitination." (PMID 38594256, 2024). "Clorgyline, a MAOA inhibitor, effectively suppresses tumor development in mice, increasing caspase three levels and decreasing IL-6, pSTAT3, STAT3, and CD44 production in tumor cells." (PMID 39092186, 2024). "The results revealed that inhibition of FGL1 expression partly attenuated the effects of Stat3 overexpression on tumor cell proliferation, migration, and invasion." (PMID 39085849, 2024). "Excessive STAT3 activation in cancer cells and the tumor microenvironment can be viewed as a neoplastic mimic of an inflammation-driven repair response that collectively drives tumor progression." (PMID 39346560, 2024). "This growth is further facilitated by the activation of STAT3, which is highly expressed in tumor tissues and regulates essential malignant biological processes such as cell growth, proliferation, and angiogenesis." (PMID 39906672, 2024). "STAT3 governs the transcription of genes that facilitate tumor infiltration, cancer cell proliferation, and resistance to chemotherapy." (PMID 38807601, 2024). "IL-6 and G-CSF from stromal or tumor sources can activate STAT3 signaling, resulting in an increase in suppressive immune effects of PMN-MDSCs by enhancing C/EBPβ expression and inhibiting IRF8 expression." (PMID 38689325, 2024). "We have previously shown that HPV8-CER:STAT3+/–tg mice had WT levels of Tyr705 STAT3 phosphorylation and demonstrated a 4-fold reduction in tumor formation." (PMID 38916963, 2024). "After IL-6 receptor activation, STAT3 inhibits the transcription of tumor suppressor microRNAs including miR-34a." (PMID 39555068, 2024). "STAT3′s involvement in tumorigenesis includes downregulation of anti-tumor immune surveillance, epithelial-to-mesenchymal transition (EMT) with subsequent metastasis, and development of drug resistance." (PMID 38339245, 2024). "STAT3 is a transcription factor involved in tumor initiation, progression, malignant behavior, and chemotherapy resistance." (PMID 38605477, 2024). "To date, studies for IL-6-mediated STAT3 activation within the tumor microenvironment mainly focus on tumor cells, T cells, and DC cells." (PMID 38274367, 2024).
tumor (continued). "STAT3 signaling is involved in antitumor immunity through multifaceted crosstalk between cancer and tumor-infiltrating immune cells in the tumor microenvironment." (PMID 38339245, 2024). "Signal transducer and activator of transcription 3 (STAT3) is a transcription factor with broad effects on controlling tumor growth and the immune response." (PMID 39402302, 2024). "These Exos harbor FGD5-AS1 and IL-6 with the potential to increase tumor cell metastasis and survival via the promotion of M2 TAMs via the STAT3/NF-κB pathway." (PMID 38360641, 2024). "In SA region, the expression of CRP (P = 0.048), gp-130 (P < 0.001), JAK2 (P = 0.004), and IL-6 (P = 0.001) was lower in tumor tissues compared with normal tissues, while the expression of IL-6R (P = 0.191) and STAT3 (P = 0.960) was comparable." (PMID 38881895, 2024). "When cytokines and growth factors are activating STAT3, it leads to tumor growth and hinders anti-tumor immunity." (PMID 39169396, 2024). "IL-6 derived from RAW264.7 further enhanced the metastatic properties of 4T1 cells in vitro and promoted tumor progression in vivo by inducing stem cell-related transcription factor expression through the STAT-3 pathway." (PMID 38355711, 2024). "STAT3 also influences tumor migration, invasion, angiogenesis, and cell survival through elevated MMP-2, MMP-9, and EMT-related gene expressions, often activated by IL-11." (PMID 38231464, 2024). "Phosphor-STAT3 staining was a strong positive in approximately half of the tumor cells from the untreated SW480 tumors and HT-29, and decreased in the treated groups of SW480 and HT-29." (PMID 38256960, 2024). "This reduction was accompanied by decreased protein levels of HIF-1α, PD-L1, VEGF, and p-STAT3 in the tumor tissues." (PMID 39690423, 2024). "Consistent with our findings in vitro, 1G11 inhibited tumor growth in mice and reduced p-STAT3 expression in tumor tissues, as confirmed by IHC." (PMID 39169307, 2024). "In conclusion, IL-6 secreted by senescent tumor cells facilitates macrophage CD73 expression via the JAK/STAT3 signaling pathway." (PMID 38323313, 2024). "Studies have shown that celecoxib, when used as an antitumor agent, can reduce tumor differentiation and metastasis by suppressing the STAT3/NF-κB axis." (PMID 39834817, 2024). "DLBCL cells express both IL-10 and its receptor, eliciting an autocrine pathway of STAT3 activation that fuels tumor cell proliferation." (PMID 39281678, 2024). "The expression levels of gp130 and the downstream targets c-Myc, cyclin D1 and Bcl-xL and the p-STAT3/STAT3 ratio were lower in the ART1-sh-transplanted tumours than in the NC tumours (P < 0.01)." (PMID 38504172, 2024). "We have previously found that NCAPD3 was highly expressed in PCa and CRC to promote tumor progression through STAT3 upregulation of MALAT1." (PMID 38561330, 2024). "The inflammatory environment is a common microenvironmental state in tumor tissues, centered on critical inflammatory pathways such as STAT3, NF-kB, which facilitate interaction between CAFs and tumor cells." (PMID 39680287, 2024). "Insulin-like growth factor binding protein 2 (IGFBP2) contributes to the activation of the STAT3 signaling pathway, leading to Treg differentiation and the creation of a suppressive tumor environment." (PMID 38902779, 2024). "The authors also evaluated the effects of manipulating the miR-4458/STAT3/PD-L1 axis on anti-tumor immunity in xenograft LLC mice." (PMID 39343796, 2024). "The IL-6/JAK2/STAT3 pathway is involved in various biological processes, including tumor cell proliferation, apoptosis, migration, invasion, and cell cycle progression." (PMID 39845783, 2024). "The JAK/STAT3 signaling pathway is vital in mediating the effects of IL-6 on tumor cell proliferation, survival, invasion, and metastasis." (PMID 39136000, 2024). "The reciprocal modulation between the CXCL12/CXCR4/ACKR3 axis and the STAT3 signaling pathway plays a crucial role in the progression of various diseases and neoplasms." (PMID 38920657, 2024).
tumor (continued). "When xenograft mice received doxorubicin with SBT-100, a STAT3 inhibitor, the osteosarcoma tumor growth was significantly suppressed, and survival of the mice increased to 71%." (PMID 36902166, 2023). "have shown that METTL3 depletion in macrophages activates the NF-κB pathway and STAT3 signaling, resulting in increased infiltration of M1 and M2 TAMs and Treg cells into the tumor, ultimately remodeling the tumor microenvironment." (PMID 38187373, 2023). "IL-6 activates JAK/STAT3 signaling, which drives tumor proliferation, survival, invasiveness, angiogenesis and immunosuppression." (PMID 37709737, 2023). "Recent data showed that the blockage of the IL-6/STAT3 pathway results in the activation of apoptosis, thus suggesting that new regulators of STAT3 in tumours are important targets for potential therapeutic strategies in the treatment of cancer." (PMID 37298475, 2023). "In both in vitro and in vivo models, the HNC018 showed anti-tumor properties via downregulating the c-MET/STAT3/AKT signaling axis in HNSCC." (PMID 37373393, 2023). "IL‐6/JAK/STAT3 signaling can drive tumor cell proliferation, invasion, and metastasis in the TME, and strongly inhibit the antitumor immune response." (PMID 38063246, 2023). "Targeted inhibition of JAK/STAT3 pathway can lead to reversal of immunosuppression and activation of immune cells to attack the tumor, resulting in decreased tumor growth and enhanced anti-tumor immune response." (PMID 38038814, 2023). "IL-6, secreted by CAFs, promotes STAT3 activation and, thus, tumor invasion and metastasis formation." (PMID 37371856, 2023). "Our in vitro study revealed the differences between PI3K/Akt and JAK/STAT3 pathway in contributing to tumor stromal cells’ influence on thyroid CSCs." (PMID 36982542, 2023). "In a xenograft assay, DGG-100629 inhibited tumor growth by lowering STAT3 activity and the expression of its target genes." (PMID 37121974, 2023). "Studies have shown that the sustained activation of STAT3 in T cells and myeloid cells at primary tumor sites promotes tumor angiogenesis, immunosuppression, tumor survival, and metastasis." (PMID 36714534, 2023). "STAT3 hyperactivation promotes several cancer-related processes, such as tumor-cell proliferation, survival, invasiveness, anti-apoptosis, angiogenesis, and formation of metastases." (PMID 37762522, 2023). "STAT1 and STAT3 are also being explored for their tumor immunity-specific functions due to the increasing importance of immunotherapy, which refers to treatments that use the body’s own immune system to combat diseases." (PMID 38022653, 2023). "Silencing STAT3 not only suppresses tumor cell proliferation and promotes anti-tumor immune responses but also enhances the anti-cancer efficacy of tumor suicide gene therapy." (PMID 37663132, 2023). "IL-6 and IL-10 cytokines activate STAT3 on T cells, which is usually related to poor cytotoxicity and anti-tumor immune response." (PMID 36911202, 2023). "Mouse xenograft transplantation assays was conducted to validate the obtained findings on the relationship between STK24 and STAT3/VEGFA signaling pathway in tumor angiogenesis." (PMID 36720310, 2023). "An inhibitory immune microenvironment that immunosuppressed regulatory T cells, myeloid-derived suppressor cells, and tumor-associated macrophages, is associated with the over-activation of pathways, including PD-1, IDO, TGF-β, STAT3, VEGF, and IL-10." (PMID 37329384, 2023). "The response was dependent on the presence of Tregs, as WP1066 was able to inhibit FoxP3+ Treg induction through the inhibition of p-STAT3, contributing to the anti-tumor response." (PMID 37741983, 2023).
tumor (continued). "The activation of STAT3 enhances M2-type polarization, and contributes to the formation of tumor-related phenotypes." (PMID 37744063, 2023). "Our research indicates that treating with ferulic acid significantly reduces the expression of mTOR and STAT3, leading to a decrease in the tumor." (PMID 37465088, 2023). "There is increasing evidence that links IL-6/STAT3 to the functional properties of the cells thatform the tumor microenvironment." (PMID 37720284, 2023). "It has been reported that RUNX1 regulated tumor function by activating downstream STAT3 and transcriptionally regulating EGFR gene expression." (PMID 38057816, 2023). "Intraperitoneal injection of recombinant IL11 (reIL11) in tumor-bearing Il11−/− mice boosted tumor growth, while STAT3 knockdown diminished such pro-tumor effect in vivo." (PMID 37365574, 2023). "Preclinical studies with Stattic showed that there was a STAT3 blockade resulting in inhibition of stemness, angiogenesis, metastasis, therapy resistance, and tumor growth." (PMID 37173951, 2023). "Blocking STAT3 elevated the expression levels of DCs that are triggered by the innate immune system, enhances the production of chemokines and cytokines in tumor tissues, triggers tumor T‐cell responses, and mediates the body's immune response." (PMID 37441462, 2023). "Results of IHC assays used to determine the density of microvessels in tumors showed that silencing of STAT3 abrogated STK24-mediated tumor angiogenesis." (PMID 36720310, 2023). "Immunohistochemical analysis of tumor sections from the recipient mice also showed rescue of phosphorylation of Stat3 and tumor cell proliferation as measured by Ki67 staining by ectopic expression of OPN in Fip200 KO cells." (PMID 36813768, 2023). "Activated STAT3 in tumor cells is a crucial mediator of oncogenesis and the cancer-related inflammation process." (PMID 37371647, 2023). "In this study, we showed that ROS, phospho-Src, phospho-STAT3, and vimentin were more abundant at the tumor boundary from HNSCC patients." (PMID 36446524, 2023). "For example, L1CAM promoted STAT3 activation via the IL-6/IL-6Rα axis to regulate tumor angiogenesis and vessel stabilization." (PMID 37248458, 2023). "Although STAT3 degradation by SD-36 can induce tumor cell apoptosis, STAT3 also has multiple vital biological functions in a variety of tissues and cell types." (PMID 37526084, 2023). "The JAK/STAT3 is a classical intracellular signaling pathway in the regulation of tumor cell proliferation, survival, invasiveness, and metastasis." (PMID 37103357, 2023). "Transcriptional profiling of autophagy-deficient tumor cells and additional mechanistic analysis determine that autophagy plays a role in regulating Osteopontin expression and its down-stream Jak/Stat3 signaling in tumor cell proliferation and tumorigenicity." (PMID 36813768, 2023). "In a study conducted by Jiang, TLR9 was found to be directly upregulated by freshly formed NETs, leading to stimulation of the NFκB, MAPK, and STAT3 pathways in tumor cells." (PMID 37365190, 2023). "At the same time, TAMs activate tumor cells by activating transcription factors (STAT3 and NF-κB) to produce VEGF and matrix metalloproteinases (MMPs) to promote tumor angiogenesis." (PMID 37513975, 2023). "In NSCLC, STAT3 activation within cancer or immune cells favors an immunosuppressive tumor microenvironment and supports an inflammatory state that promotes tumor growth." (PMID 36672335, 2023). "miR-3619-5p inhibited tumor growth in vivo by inducing the phosphorylation of activator of transcription 3 (STAT3) and retinoblastoma protein (Rb1), thereby targeting PSMD10 to inhibit cell proliferation and induce G1 arrest." (PMID 37349676, 2023). "The key difference is derived from differential STAT activation between the tumor (STAT3) and the hair follicle (STAT5) epithelium." (PMID 37164949, 2023).
tumor (continued). "The tumor samples of most NSCLC patients display persistently activated STAT3, and this upregulated expression correlates with an advanced clinical stage, metastasis to lymph nodes, and drug resistance." (PMID 36672335, 2023). "In humans, hyperactivated STAT3 affects the development and progression of cancer by promoting tumor invasion, tumor-cell proliferation and survival, angiogenesis, and immunosuppression." (PMID 37240202, 2023). "Tumor cells interact with astrocytes through gap junction, paracrine, exosomes, and STAT3 expression." (PMID 37056723, 2023). "To further investigate the specific mechanism by which ANXA2 affects the inflammatory response, we found that ANXA2 is able to stimulate tumour cell proliferation by altering STAT3 phosphorylation levels." (PMID 36932468, 2023). "This phenomenon leads to tumor evasion from immune surveillance via autophagy-mediated activation of the STAT3 signaling pathway." (PMID 36833401, 2023). "Our results demonstrate that the absence of MTDH significantly reduces IBC cell migration, proliferation, tumor spheroid formation, and the expression of NF-κB and STAT3 signaling molecules, which are crucial oncogenic pathways in IBC." (PMID 36902125, 2023). "Various studies have shown that the hyperactivation of STAT3 enhances the expression of its target genes, leading to an increase in tumor cell migration and proliferation, and thus contributing to colorectal carcinogenesis." (PMID 36982677, 2023). "Herein, we evaluated if the expression of E-cadherin, STAT3, NF-κB, CD163, PD-L1, and CXC12 would be associated with a poor prognosis for patients with tumours with low (1/2) and high (3/4) modified Dukes’ classification in primary CRC." (PMID 36857852, 2023). "Another strategy tumor cells use to keep STAT3 active is the production of large amounts of IL-6, which is used in an autocrine manner to signal via its receptor (IL6R) and maintain sustained STAT3 phosphorylation." (PMID 37372319, 2023). "JAK2 belongs to the Janus Kinases family of protein tyrosine kinases that plays an important role during tumor progression through STAT3 phosphorylation." (PMID 36740668, 2023). "In the lung, when STAT3 is aberrantly activated within myeloid cells, it promotes the development of cancer by recruiting the tumor microenvironment immune cells that have immunosuppressive functions." (PMID 36672335, 2023). "This provides a testament to Leo’s capacity to exert an anti-neoplastic influence on tumor cells, especially those displaying drug resistance, via the modulation of STAT3-related signaling pathways." (PMID 37818195, 2023). "To further investigate the underlying mechanism of co-treatment therapy, we examined several major downstream signaling molecules of tyrosine kinases, including Stat1 and Stat3, in tumor tissues isolated at the end of the pharmacodynamic assay." (PMID 37375842, 2023). "Taken together, these data indicate that TCAF2 in TPCs induces Wnt5a secretion and activates STAT3, thus promoting tumor cell EMT and facilitating CRCLM." (PMID 37635201, 2023). "in skin cancer supports this possibility, as overexpression of STAT3 promoted tumor progression by stimulating the angiogenic effects of IL-17+ Th17 cells." (PMID 37680632, 2023). "Collectively, there is evidence of a STAT3/VEGF activation loop that perpetuates OvCa progression through the support of vascular development within the tumor microenvironment." (PMID 37173951, 2023). "STAT3 is also critical in inhibiting antitumor immune response by suppressing the expression of tumor immune activators and promoting the production of immunosuppressive factors." (PMID 37334274, 2023). "In contrast, tumor suppressor miRNAs inhibit oncogene pathways such as STAT3, LRP8, and TACC1 to suppress CP resistance." (PMID 37371458, 2023). "Autophagy and STAT3 pathways are two important directions in tumorigenesis and progression, and both have become research hotspots for tumor mechanisms in recent years." (PMID 37063281, 2023).